IL1B (interleukin 1 beta)
Diseases named in the same sentence as IL1B in open-access papers (continued):
Sharing a sentence is not in itself a finding about the gene and the disease.
Granuloma (50 papers, 2008 to 2026). A compact, organized collection of mature mononuclear phagocytes, which may be but is not necessarily accompanied by accessory features such as necrosis. "Pro-inflammatory cytokines, especially TNF-α, IL-6, IL-1β, and IL-8, not only induce inflammation but also cause leukocyte infiltration, granuloma formation, and tissue fibrosis." (PMID 34681651, 2021). "MWCNT entering the airways of mice have been shown to elicit several pro-inflammatory events that originate from their activation of the NLRP3 inflammasome and are associated with the induction of IL-6, TNF-α, and IL-1β, formation of granulomas and development of airway fibrosis." (PMID 29922162, 2018). "XTMAB-16 inhibited granuloma formation and suppressed interleukin-1β (IL-1β) secretion in the in vitro granuloma model with a half maximal inhibitory concentration (IC50) of 5.2 and 3.5 μg/mL, respectively." (PMID 37021060, 2023). "In addition, IL-1β, linked to sarcoidosis in a number of recent publications, appears to be a reliable predictor of granuloma response in this model and, therefore, could act as a biomarker for response in future studies." (PMID 37021060, 2023). "Predicted Cavg and Ctrough of XTMAB-16 in lung tissue approximate the IC50 values for reduction in granuloma formation and IL-1β in the in vitro granuloma model." (PMID 37021060, 2023). "Cytokines such as IL-1β, IL-4 IL-5, IL-6, IL-13, TNF-α, MCP-1, and TSLP induce allergy-related inflammation, which causes tissue fibrosis, granuloma formation, and leukocyte infiltration." (PMID 36235405, 2022). "In the young/middle-aged, only IL-1β showed a difference and was significantly higher in granulomas (p = 0.019)." (PMID 35053012, 2021). "While CBA mice develop large egg granulomas and severe disease due to CD209a activation to produce IL-1β and IL-23 and to induce Th17 cells, BL/6 mice develop smaller lesions, explained by a disability to induce Th17 response by the CD209a recognition pathway." (PMID 34970264, 2021). "In LZD+IL-1Rn treated granulomas we found a strong positive correlation between IL-1β levels and fold-change in SUVR, a surrogate for inflammation." (PMID 32477361, 2020). "Il-1β has been shown to be upregulated in the onset and formation of M. marinum and M. tuberculosis granulomas." (PMID 30552162, 2019). "This proinflammatory environment has been observed in human TB, with Il-1β found to be in high levels in pleural fluid from TB patients with granulomas present." (PMID 30552162, 2019). "The messenger RNAs of proinflammatory cytokines TNF-α, IL-1β, and IL-6, which initiate the fibrotic process, have been demonstrated in macrophages located at the periphery of granulomas." (PMID 30037796, 2018). "Early studies showed the importance of IL1β in granuloma formation, whereby coated beads were capable of inducing large granulomas in lung tissue." (PMID 28747644, 2017). "Of interest, IL-1R1−/− mice, consistent with previously reported findings in IL-1β−/− mice, produced high numbers of granulomas in response to infection." (PMID 25114104, 2014). "We demonstrated that the level of IL-1β was significantly reduced in granulomas from infected SOM−/− mice which correlated with reduced parasite burden." (PMID 25530957, 2014). "We also observed an increased proportion of granulomas in the jejunum of IL-1β−/− mice suggesting that Hp larvae are forced to invade the intestine at a more distal location." (PMID 23935505, 2013). "IL-1β signaling has been reported to play an important role in the control of mycobacterial infection and granuloma formation." (PMID 22558425, 2012). "This cascade culminates in the expression of many NF-κB-inducible genes, including CCL2, IL1B, IL12, IL18 and TNF, causing natural killer (NK) and T cells to release IFN-γ and TNF-α, which ultimately results in granuloma formation." (PMID 22182502, 2011).
Granuloma (continued). "Enrichment analysis revealed upregulated immunological pathways related to granuloma formation in pulmonary sarcoidosis PBMCs, including T helper 17 and tumor necrosis factor-alpha signaling pathways, IL-1B, IL-6, and IL-17 production, and response to external stimuli." (PMID 41463010, 2025). "Additionally, the increased expression of IL-1β can be observed inside granulomas in patients with sarcoidosis." (PMID 39180528, 2024). "This process may also explain why, in the present study, adult patients had significantly higher levels of IL-1β in granulomas (p = 0.0019)." (PMID 35053012, 2021). "In our study, there was a greater expression of IL-1β in granulomas only in the adult patients." (PMID 35053012, 2021). "However, in the comparison of the pro-inflammatory cytokines between cyst and granulomas, there was a significant difference only in relation to IL-1β (p = 0.019), which showed a greater expression in granulomas." (PMID 35053012, 2021). "Similarly, our present observations indicated that higher expression levels of both IL-1α and IL-1β were found in the granuloma group compared to those in cyst and control groups." (PMID 30012121, 2018). "This reduction in parasite burden in SOM−/− mice was accompanied by a 95% increase in size of their granulomas (P < 0.05), which contained a 1.5-fold increase in levels of IFN-γ and a 26-fold decrease in levels of IL-1β (P < 0.05 for both) compared to granulomas from WT mice." (PMID 25530957, 2014). "In addition, an increase in acute phase reactive serum glycoproteins, together with neutrophil infiltration and increased of IL-1β production indicated an early inflammatory response before granuloma formation." (PMID 24098654, 2013). "Therefore neutrophil-derived IL-1β may contribute to the containment of the disease through the recruitment of macrophages to sites of infection and the subsequent granuloma formation." (PMID 28747644, 2017). "In addition Schistosoma-induced granulomas have been shown to secrete IL-1β during the early phase of their formation, and to modulate gastrointestinal neuromuscular function suggesting a role for IL-1β in the altered contractility profiles observed in schistosomiasis." (PMID 26635531, 2015). "We hypothesize that the same effect observed in T. gondii infection may be occurring in T. crassiceps infection; IL-1β may stimulate growth of cysts in the peritoneum of infected WT mice and its reduction in the granulomas of SOM−/− mice impairs cyst growth in the peritoneum of these animals." (PMID 25530957, 2014). "Producing the pro-inflammatory cytokines IL-1β and TNF-α helps inhibit Mtb infection in granulomas and prevent the spread of Mtb." (PMID 37818041, 2023). "The data revealed elevated expression of IL-1β, IL-6, and TNF-α, all known to reflect the pathogenesis of sarcoidosis, in the in vitro granuloma model." (PMID 38038136, 2023). "The presence of cytokines, to as IL-1β, IL-6 and TNF-a, suggest that these cytokines have a role in granuloma formation in to patients." (PMID 35672755, 2022). "Smoking is thought to trigger systemic increases in cytokines, such as IL-6, IL-1β, and TNF-α, which are critical in the formation of granulomas." (PMID 32872212, 2020). "Considering their crucial roles in fish inflammatory response, especially in the large yellow croaker, IL-6 and IL-1b may play important roles in the immune response of E. coioides to P. plecoglossicida during the process of white spot disease, and are closely related to the formation of granuloma." (PMID 31130962, 2019). "Decreasing the size of granuloma tissue, it is well correlated with decreased pro-inflammatory cytokines levels (e.g., TNF-α, and IL-1β), as well as an increased level of IL-10." (PMID 30823424, 2019). "TNF, IL-1β, IL-18, IL-1RA, IL-8, MCP-1, and MIG were all present at significantly (p<0.05–0.0001) lower levels in secondary granulomas, with a trend towards lower IFN-γ." (PMID 30312351, 2018).
Granuloma (continued). "Interestingly, mice singly deficient for IL-1α or for IL-1β developed some granuloma with limited oedema, no necrosis and free alveolar space, thus a much less severe lung pathology than that seen in the absence of both IL-1α and IL-1β or of IL-1R1 at 5 weeks post-infection." (PMID 25400917, 2013). "In human livers with hepatic AE, the mRNAs of pro-inflammatory cytokines, interleukin (IL)-1β, IL-6, and TNF-α have been found in macrophages located at the periphery of granulomas, in those areas which were shown to be at the initiation of fibrogenesis." (PMID 23405141, 2013). "Therefore, we performed linear regression analyses comparing cytokines detected by multiplex and granuloma inflammation (FDG SUVR) and found a positive correlation between IL-1β and fold change of SUVR in LZD+IL-1Rn granulomas." (PMID 32477361, 2020). "In granulomas, levels of IL-1β, IL-1RA, and IL-18 were not affected by IL-1Rn treatment in the subset examined." (PMID 32477361, 2020). "However, our data indicate that suppression of IL1β per se is not sufficient to abrogate the angiogenic response to the granulomas." (PMID 28332618, 2017). "Our data would support this hypothesis because we saw severe granuloma-like lesions in the lungs of the CDC1551 and ΔsigC complemented mutant groups but not among the ΔsigC mutant infected mice where a lower concentration of IL-1β was detected." (PMID 18798983, 2008). "Indeed, we recently showed that mice lacking IL-1β, IL-1α or IL-1R and treated with DQ12 silica presented a reduction of chronic lung inflammation and granuloma formation compared to their WT counterparts." (PMID 25497724, 2014).
myeloma (50 papers, 2008 to 2026). "This study aimed to investigate the association of IL1B gene polymorphism and interleukin-1β plasma concentration with the occurrence of nutritional disorders and survival in patients with multiple myeloma." (PMID 38610941, 2024). "Determination of IL1B polymorphism may be a useful predictive marker of the risk of cachexia and prognostic factor in multiple myeloma patients." (PMID 38610941, 2024). "Pairwise protein analysis confirmed cosecretion of IL-1β and IL-6 in macrophages stimulated with IL-4/IL-13, which were identified as part of a critical pathway in multiple myeloma before." (PMID 42292686, 2026). "In myeloma studies, IL-1a and IL-1β have been shown to work synergically with IFN-γ to induce tumor-killing activity in tumor-infiltrating macrophages." (PMID 40244135, 2025). "Overall, a large fraction of myeloma cells in the population responded to IL-1β CM, including a substantial fraction of hyper-responders." (PMID 39370432, 2024). "Next, we measured the levels of M-CSF and RANKL, which mediate normal osteoclast differentiation, and those of pathological osteoclastogenic inflammatory IL1β and TNFα in the serum obtained from patients with multiple myeloma using ELISA." (PMID 38683225, 2024). "There is contrary evidence from a limited number of studies that IL-1β can have tumor-inhibiting effects, specifically by inducing both T helper cell 1 (Th1) and Th17 anti-tumorigenic effects in myeloma and lymphoma." (PMID 39475614, 2024). "Cancer cells including human multiple myeloma can induce cells to generate interleukins (IL-1α and IL-1β) or it can directly release IL-1α and IL-1β within the tumor microenvironment." (PMID 35399416, 2022). "A number of cytokines are elevated in the myeloma bone marrow microenvironment and some of them, including IL-1β, have been also reported to induce NETosis." (PMID 33218159, 2020). "The cancer‐suppressive effect of IL‐1β was confirmed in a mouse model for myeloma showing that IL‐1β (as well as IL‐1α) neutralization by anakinra severely impaired myeloma clearance by tumor‐specific Th1 cells and tumor‐infiltrating macrophages." (PMID 32770571, 2020). "Stromal and myeloma plasma cells, through autocrine stimulation of low doses of IL-1β, trigger IL-6 production, which in turn is responsible for the expansion and survival of myeloma cells." (PMID 32825489, 2020). "IL-1β release, from supernatants of drug treated myeloma cells increased significantly after 8h, as did ASC which is also assembled into a large protein complex known as a ‘speck’, and constitutes the pyroptosome." (PMID 33066043, 2020). "On the other hand, in myelomas, versican is proteolyticaly processed to the DAMP versikine, which induces the secretion of IL-1β and IL-6 by human myeloma marrow-derived macrophages (MAMs)." (PMID 31068944, 2019). "IL-1β is an osteoblast activating factor which plays an important role in the bone lesion by multiple myeloma cells, and promotes the proliferation of myeloma cells by inducing IL-6 generation." (PMID 30211233, 2018). "An in vivo work confirmed that IL-1β has a relevant role in the conversion of latent myeloma to active MM." (PMID 29089667, 2017). "Direct evidence has shown that IL1-β plays an important role in multiple myeloma, and when released, this cytokine induces IL-6 production by bone marrow stromal cells and acts as an autocrine growth factor for myeloma cells." (PMID 28785138, 2017). "The adhesion of myeloma cells to the stromal cells prompts the bone marrow stromal cells to secrete osteoclast-activating factors (OAFs) such as IL-1β, IL-6, and TNF-β, which further induce stromal cells and osteoblasts to secrete RANKL." (PMID 24252328, 2013). "The myeloma cell adheres to the bone marrow (BM) microenvironment, and thereby stimulates angiogenesis and enhances the stimulation of cytokines such as IL–1β, IL–6 and IL–10." (PMID 22567049, 2011).
myeloma (continued). "These drugs induce apoptosis of myeloma cells, interrupt the interaction between myeloma cells and stromal cells in the BM, inhibit angiogenesis and inhibit the secretion of IL–1β and IL–6." (PMID 22567049, 2011). "Hence, our data obtained in compact 3D microenvironments show that MM1.S exposure to molecules secreted by HS-5 cells exposed to IL-1β reproduces the NF-κB activation in myeloma cells seen in mouse calvaria and patients’ BMs." (PMID 39370432, 2024). "IL-1β is a cytokine secreted by myeloma cells and it is responsible for bone resorption in MM." (PMID 38610941, 2024). "Indeed, the IL-1β antagonist (IL-1ra) Anakinra has been used to delay or prevent the progression in patients with indolent or smouldering multiple myeloma." (PMID 39370432, 2024). "Considering that SELENOW is highly expressed in multiple myeloma and that it promotes osteoclast differentiation, we analyzed the molecular mechanisms underlying SELENOW upregulation in multiple myeloma with an increase in circulating osteoclastogenic factors, including M-CSF, RANKL, IL1β, and TNFα." (PMID 38683225, 2024). "Valve opening let the IL-1β-CM to freely diffuse toward the myeloma cells." (PMID 39370432, 2024). "The suppression of IDO1 induction by carfilzomib could enhance its therapeutic activity in myeloma, a problem potentially exacerbated by the apparent ability of carfilzomib alone to induce some IL1B and IL6 expression." (PMID 35371018, 2022). "Interestingly, the use of the specific IL-1β affinity P2D7KK antibody resulted in a survival rate of 70% in a murine myeloma model." (PMID 33808304, 2021). "IL-6 and IL-1β are potent osteoclast activators in myeloma pathogenesis." (PMID 32587468, 2020). "Thus, inflammasome/pyroptosomes activation and cleavage of GSDMD and PANX1 are likely to induce pore formation leading to the “ballooning” morphology and the subsequent release of LDH and IL-1b seen in the drug treated myeloma cells." (PMID 33066043, 2020). "IL-1β gene and IL-1β protein, though less potent, are expressed in myeloma cells." (PMID 33014130, 2020). "Under such analysis, a question arises: Could anomalous IL-1b production be participating in the transformation from MGUS to myeloma?" (PMID 31185596, 2019). "An analogous process may happen in human myeloma, in which anomalous expression of IL-1b provokes augmented expression of adhesion molecules, such as CD54, CD56, CD44, and VLA-4, on monoclonal plasma cells." (PMID 31185596, 2019). "It is reported that IL-1β could promote tumor growth by inducing the release of downstream molecule IL-6 in patients with multiple myeloma." (PMID 29312552, 2017). "Thus, IL-1β plays an important role in the development of multiple myeloma." (PMID 30211233, 2018). "The importance of cytokines (eg, interleukin IL-6, IL-1β, IL-10, and tumour necrosis factor-α) and the role of cross talk between myeloma cells and the bone marrow microenvironment in the proliferation, apoptosis and migration of myeloma cells and patient survival is becoming clearer." (PMID 18813242, 2008). "In support, the pro-tumor activity of the inflammasome can be proven by the blockade of IL-1β using Anakinra, which proved to prolong the PFS of myeloma patients through the reduction of IL-6 levels, crucial for tumor cell proliferation and survival." (PMID 39857785, 2025). "Multiple myeloma patients were found to produce more osteoclastogenic factors (M-CSF, RANKL, IL1β, and TNFα) than healthy individuals." (PMID 38683225, 2024). "Other nodules in the network correspond to cytokines with known function in myeloma pathophysiology and/or in osteolytic lesions (IL6, IL1β, CCL2, IL8 and CCL20)." (PMID 25268740, 2014). "For example, IL-1β, IL-6, IL-10, IFN-α, IGF-1 and TGF-γ promote proliferation of multiple myeloma cells, whereas IFN-β1 and APO-1/FAS inhibit the growth of multiple myeloma cells." (PMID 22792345, 2012).
myeloma (continued). "IL-1b, TNF-a, IL-6, and IL-10 may contribute to osteopenia; IL-1b, TNF-a, and IL-6 may have a role in the activation of coagulation and hypermetabolism; IL-6 and IL-10 may be responsible for gammopathies and multiple myeloma." (PMID 36498496, 2022). "IL-1b, TNF-a, IL-6, and IL-10 may contribute to osteopenia; IL-6 and IL-10 may be responsible for gammopathies and multiple myeloma; IL-1b, TNF-a, and IL-6 may have a role in the activation of hypermetabolism." (PMID 36498496, 2022). "Normal plasma cells do not deliver IL-1b; nevertheless, abnormal IL-1b generation by myeloma cells has been demonstrated at both the mRNA and protein levels in numerous reports." (PMID 31185596, 2019). "Patients of POEMS have higher levels of IL-1B, TNF-alpha and IL-6 as compared to multiple myeloma." (PMID 24349810, 2013). "In addition, bone marrow stromal cells surrounding multiple myeloma display noticeably increased production of osteoclastogenic cytokines, including macrophage colony-stimulating factor (M-CSF), tumor necrosis factor-α (TNF-α), IL-6, IL-11, and IL-1β." (PMID 38683225, 2024). "A recent clinical study has shown that the CD14+ monocytes from multiple myeloma patients could be induced to differentiate into functional DCs by culturing them with the cytokine cocktail consisting of GM-CSF, IL-4, IL-6, TNF-α and IL-1β for use in cancer immunotherapy." (PMID 18533025, 2008).